PHC3 (polyhomeotic homolog 3)
Description:
Component of a Polycomb group (PcG) multiprotein PRC1-like complex, a complex class required to maintain the transcriptionally repressive state of many genes, including Hox genes, throughout development. PcG PRC1 complex acts via chromatin remodeling and modification of histones; it mediates monoubiquitination of histone H2A 'Lys-119', rendering chromatin heritably changed in its expressibility.
Synonyms: hPH3; EDR3; FLJ12967; FLJ12729
Tractability: PROTAC: UniProt records ubiquitination sites on it; ubiquitination databases record sites on it; its protein half-life has been measured.
Gene: Protein-coding gene on chromosome 3 (170,086,732 to 170,181,768, reverse strand). Ensembl gene ENSG00000173889.
Subcellular location: Nucleus
Subcellular location (Human Protein Atlas): Nucleoplasm
Pathways (Reactome):
Metabolism of proteins: SUMOylation of DNA damage response and repair proteins; SUMOylation of DNA methylation proteins; SUMOylation of RNA binding proteins; SUMOylation of chromatin organization proteins; SUMOylation of transcription cofactors
Gene expression (Transcription): RUNX1 interacts with co-factors whose precise effect on RUNX1 targets is not known; Transcriptional Regulation by E2F6
Cellular responses to stimuli: Oxidative Stress Induced Senescence
Developmental Biology: Differentiation of naive CD4+ T cells to T helper 2 cells (Th2 cells)
Signal Transduction: Regulation of PTEN gene transcription
Gene Ontology:
Molecular function: protein binding; chromatin binding; histone binding; zinc ion binding
Biological process: heterochromatin formation; negative regulation of DNA-templated transcription
Cellular component: nucleoplasm; nucleus; PcG protein complex; PRC1 complex; chromatin
Genetic constraint (gnomAD): Loss-of-function variants: 12 observed, 104.89 expected, observed/expected ratio (o/e) 0.11, 90% interval 0.072 to 0.19. The upper end of that interval is the gene's LOEUF score, 0.19, which puts it in group 1 of 6, group 1 being the genes least tolerant of losing a copy. Missense variants: 974 observed, 1,243.7 expected, observed/expected ratio (o/e) 0.78, 90% interval 0.74 to 0.83. Synonymous variants: 445 observed, 440.36 expected, observed/expected ratio (o/e) 1.01, 90% interval 0.93 to 1.09.
Homologues: Orthologues: chimpanzee PHC3 (99% identical), macaque PHC3 (99% identical), rabbit PHC3 (98% identical), dog PHC3 (97% identical), pig PHC3 (97% identical), guinea pig PHC3 (96% identical), rat Phc3 (94% identical), mouse Phc3 (92% identical), tropical clawed frog phc3 (60% identical), zebrafish phc2b (33% identical), Drosophila melanogaster ph-p (23% identical), Drosophila melanogaster ph-d (22% identical), and 1 more. Paralogues in human: PHC2 (36% identical), PHC1 (29% identical), SAMD11 (10% identical), SCML2 (10% identical), SFMBT1 (10% identical), SCMH1 (10% identical), SFMBT2 (9% identical), L3MBTL4 (9% identical), L3MBTL3 (9% identical), L3MBTL1 (8% identical), SAMD7 (8% identical), SCML4 (7% identical), and 6 more.
Diseases named in the same sentence as PHC3 in open-access papers:
PHC3 is named in the same sentence as 39 diseases in open-access papers, as found by Europe PMC text mining. Sharing a sentence is not in itself a finding about the gene and the disease. The quoted sentences say what the papers report.
osteosarcoma (5 papers, 2009 to 2025). A usually aggressive malignant bone-forming mesenchymal neoplasm, predominantly affecting adolescents and young adults. "Previous data indicated that a decreased level of PHC3 serves as an oncomarker, while the mutant allele coding for this protein is associated with a decreased viability of patients with osteosarcoma." (PMID 40003978, 2025). "PHC3 is a member of the human polycomb complex and has been implicated as a tumor suppressor of osteosarcoma." (PMID 36077848, 2022). "PHC3 (polyhomeotic homolog 3), a component of the hPRC-H complex, associates with E2F6 during G0 and is lost in osteosarcoma tumors." (PMID 20015385, 2009). "PHC3 expression was absent in a majority of primary osteosarcoma tumors, and loss of PHC3 function would favor tumorigenesis by potentially disrupting the ability of cells to remain in G0." (PMID 33569895, 2021).
lung carcinoma (2 papers, 2015 to 2021). "Compared with siRNA-control group, Knock-down of Shh inhibited proliferation of CD133+ lung cancer cells, and decreased the protein expression of PHC3 in CD133+ lung cancer cells." (PMID 34424425, 2021). "Meanwhile, the mRNA and protein expressions of Shh, Smo, Gli1 and PHC3 were highly activated in CD133+ lung cancer cells." (PMID 34424425, 2021). "Furthermore, this study revealed that SHH signaling pathway and PHC3 worked together in lung CSCs and that aberrant activation of these signals promoted the tumorigenesis and progression of lung cancer." (PMID 34424425, 2021). "To further explore whether SFN regulated SHH signaling pathway and PHC3 in lung CSCs, we examined the effects of SFN on the mRNA expression level of Shh, Smo, Gli1 and PHC3 in CD133+ lung cancer cells." (PMID 34424425, 2021). "SFN could also inhibit protein expression of Shh, Smo, Gli1 and PHC3 in the lung cancer stem cells (P < 0.01or P < 0.001)." (PMID 34424425, 2021). "SFN might be an effective new drug which could inhibit self-renewal of lung cancer stem cells through the modulation of Sonic Hedgehog signaling pathways and PHC3." (PMID 34424425, 2021). "Sonic Hedgehog signaling pathway might undergo a cross-talk with PHC3 in self-renewal of lung cancer stem cells." (PMID 34424425, 2021). "In addition, SFN inhibited the activities of Shh, Smo, Gli1 and PHC3 in CD133+ lung cancer cells." (PMID 34424425, 2021). "Knock-down of PHC3 also affected the proliferation and decreased the Shh expression level in CD133+ lung cancer cells." (PMID 34424425, 2021). "Importantly, the results revealed that SFN is a potent drug preventing lung cancer cell growth through regulating SHH signaling pathway and polycomb group molecule PHC3." (PMID 34424425, 2021). "As no prior report on the relationship between SHH and PHC3 in lung cancer existed, we employed a further study expression of PHC3 in siRNA-Shh transfected cells." (PMID 34424425, 2021).
gastric cancer (1 paper, 2025). A primary or metastatic malignant neoplasm involving the stomach. "BIRC5, CLDN1, DDX58, IL18, NPC2, NUSAP1, and PHC3 were found to have higher expression in gastric cancer tissues compared to normal tissues, and their expression was also elevated in various other cancer types." (PMID 40393971, 2025).
ovarian serous carcinoma (1 paper, 2021). "In addition, PHC3 also was found to be frequently up‐regulated in three common epithelial neoplasms (lung SCC, uterine carcinoma and ovarian serous carcinoma), which may act as a potential oncogene." (PMID 33569895, 2021).
tumor (31 papers, 2011 to 2026). "The experiments confirmed upregulation of circ-PHC3 in OC tissues compared with matched non-tumor tissues, consistent with RNA-seq data." (PMID 37468993, 2023). "Our results showed high expression of hsa_circ_0005228 (circ-PHC3) in OC tissues, distinct from other tumor types." (PMID 37468993, 2023). "Downregulation of circ-PHC3 enhanced miR-497-5p expression while miR-497-5p inhibition led to recovery of the proliferation and invasion abilities of tumor cells under conditions of circ-PHC3 silencing." (PMID 37468993, 2023). "Immunohistochemical Ki67 staining showed inhibition of Ki67 expression under conditions of circ-PHC3 silencing, clearly indicating that downregulation of circ-PHC3 suppresses OC cell proliferation and tumor growth." (PMID 37468993, 2023). "To reveal the effects of circ-PHC3 on the proliferation and tumor growth of OC, we generated siRNA against circ-PHC3 for transfection into OV90 and SKOV3 cells." (PMID 37468993, 2023). "To reveal the effects of circ-PHC3 on tumor stem cell differentiation, we performed tumor sphere formation assays in both SKOV3 and OV90 cells." (PMID 37468993, 2023). "Agents such as sulforaphane inhibit CSC self-renewal by disrupting Hh activity and downregulating polyhomeotic homolog 3 (PHC3), while PHC3 interacts with the Hh pathway to maintain the survival of tumor stem cells." (PMID 41522355, 2026). "In an in vivo xenograft mouse model, tumor volumes and weights of nude mice injected with SKOV3 cells transfected with circ-PHC3 siRNA were decreased." (PMID 37468993, 2023). "We observed significant differences in expression patterns of specific circRNAs, such as circ-PHC3, between tumor and non-tumor tissue counterparts." (PMID 37468993, 2023). "Similarly, the lncRNA LINC01133 may regulate the activity of tumor suppressor pathways by dysregulating ACTL6A, SMARCD2, SMO, PHC3, and CENPP." (PMID 34925461, 2021).
cancer (20 papers, 2014 to 2025). A tumor composed of atypical neoplastic, often pleomorphic cells that invade other tissues. "This generates an apparent contradiction, as both the hypofunction and hyperfunction of PHC3 show an association with cancer." (PMID 40003978, 2025). "Mutational alterations to or the amplification of PHC3 have been linked to various forms of cancer." (PMID 40003978, 2025). "PHC3-PRKACA was classified as ‘cautionary’ PP-SV, as PHC3 showed potential cancer suppressor effect in PCa, while PRKACA appears to portray oncogenic behaviour." (PMID 38947031, 2024). "The collective findings support the theory that circ-PHC3 influences cancer stem cell differentiation through regulation of the miR-497-5p/SOX9 axis." (PMID 37468993, 2023). "Downregulation of circ-PHC3 led to suppression of OC malignant progression in both in vivo and in vitro, suggesting a critical function in cancer progression." (PMID 37468993, 2023). "Future molecular studies are required to carefully dissect the role of PHC3 in different human cancers." (PMID 33569895, 2021). "The second network contained 6 of the identified autoantigens (AGO1, CSNK1G1, IFIT5, PHC3, SRP19, and UBE2S) out of the 35 molecules associated with cancer, organismal injury and abnormalities." (PMID 31494269, 2019). "Notably, overexpression of SOX9 and miR-497-5p inhibition led to recovery of stemness in OC cells, suggesting that circ-PHC3 affects cancer stem cell differentiation through regulation of the miR-497-5p/SOX9 axis." (PMID 37468993, 2023). "Thus, circ-PHC3 appears to exert effects on cancer stem cell differentiation through regulation of the miR-497-5p/SOX9 axis." (PMID 37468993, 2023). "PHC3-PRKACA was classified as ‘cautionary’ PP-SV, as PHC3 showed a potential cancer suppressor effect in PCa, while PRKACA appears to portray oncogenic behaviour." (PMID 40064858, 2025).
infection (7 papers, 2012 to 2026). The state of being infected such as from the introduction of a foreign agent such as serum, vaccine, antigenic substance or organism. "The results showed that DYRK1A, FAM135A, PLAG1, ZNF148, and PHC3 were obviously inhibited at infection times of 3 h, 6 h, and 9 h pi." (PMID 31784561, 2019). "Downregulation of 4 miRNA target genes, including PLAG1, ZNF148, PHC3, and DYRK1A, was first found in CVB3-infected cells, though 4 genes were associated with nonenterovirus replication and infection." (PMID 31784561, 2019).
PHC3 also shares sentences with these, for which no sentence is quoted: cyst (6 papers); glioma (5); primary hyperoxaluria (3); breast carcinoma (2); colorectal cancer (2); microcephaly (2); ovarian carcinoma (2); Stroke (2); Ad (1); ameloblastoma (1); Anxiety (1); bacterial infection (1); brain tumor (1); cardiac hypertrophy (1); cardiovascular diseases (1); coloboma (1); cystinuria (1); Dent disease (1); depression (1); Epithelial dysplasia (1); epithelial neoplasm (1); fungal infections (1); Hyperoxaluria (1); lung diseases (1); lymphoma (1); melanoma (1); metastatic tumors (1); prostate carcinoma (1); prostate tumors (1); renal fibrosis (1).
A further 2 diseases each share a sentence with PHC3 in 1 paper.